EGFR (epidermal growth factor receptor)
Diseases named in the same sentence as EGFR in open-access papers (continued):
Sharing a sentence is not in itself a finding about the gene and the disease.
breast carcinoma (continued). "We noticed a remarkably low incidence of EGFR protein expression (1.3%) while analyzing the spectrum of molecular subtypes of breast cancer in a Saudi population by immunohistochemistry." (PMID 21702909, 2011). "Numerous studies have demonstrated that HER2 is often co-expressed in breast cancers with epidermal growth factor receptor (EGFR)." (PMID 21961653, 2011). "Herein we report the prevalence of EGFR protein expression and gene amplification in a cohort of Saudi breast cancer patients." (PMID 21702909, 2011). "EGFR signaling has previously been shown to play a role in the galvanotaxis of several cell types including keratinocytes, breast cancer cells, corneal epithelial cells, and embryonic NPCs." (PMID 21909360, 2011). "We believe that this assay has the potential to act as a prognostic test in HER2 and EGFR positive breast cancer although much more validation work is required." (PMID 21908901, 2011). "Our studies suggest that the window of opportunity for effective breast cancer prevention using EGFR inhibitors is a state at which loss of BRCA1 and gain of EGFR have occurred, but the growth factor independence of cancer cells has not yet been established." (PMID 21396117, 2011). "HER2 (ErbB2) is a surface protein and member of the epidermal growth factor receptor (EGFR) family that is overexpressed in approximately one-fifth of breast cancers." (PMID 21203579, 2010). "This study investigated the expression of CXCR4, CCR7, CXCL12, CCL21, and EGFR to illustrate the role of these biomarkers in breast cancer metastasis and prognosis." (PMID 20181250, 2010). "Together, these results provide a rationale for targeting EGF-like factors (HB-EGF, AREG and TGF-α) and proteases (MMP1 and ADAMTS1) in tumour cells, as well as EGFR in osteoblasts for controlling osteolytic bone metastasis of breast cancer." (PMID 20010942, 2010). "In contrast, nuclear EGFR was detected in epithelial cells from normal mammary glands removed from spontaneous breast cancer-bearing TA2 mice as well as in breast cancer cells from those animals." (PMID 20092659, 2010). "The correlation of PIPKIγ with EGFR/HER family receptors is consistent with the finding that PIPKIγ expression is inversely correlated to the survival of breast cancer patients." (PMID 20074374, 2010). "Oleic acid has been shown to activate EGFR signalling in both endothelial and breast cancer cell lines." (PMID 19997104, 2010). "For instance, patients with breast cancer overexpressing HER2/neu proto-oncogene of the epidermal growth factor receptor (EGFR) family who were treated with trastuzumab/Herceptin (anti-HER2) have a high rate of brain metastases." (PMID 20419092, 2010). "Epidermal growth factor receptor (EGFR)/human epidermal growth factor receptor (HER) family receptors are often overexpressed in breast cancers and are used as breast cancer biomarkers." (PMID 20074374, 2010). "HER2/Neu/ErbB2 is a member of the epidermal growth factor receptor (EGFR) family that is amplified and overexpressed in 20%–30% of breast carcinomas." (PMID 21113302, 2010). "In this study, it was observed that patients with high EGFR expression are more prone to developing metastasis and possessing high grades of tumor, which are both important prognostic factors for breast cancer patients." (PMID 20181250, 2010). "To characterize breast carcinomas with the PALB2 mutation more specifically, we evaluated the expression of CK5/6, CK14, CK17, EGFR and CD117." (PMID 20122277, 2010). "In ER- breast cancer, IL12, IL2 and IFNG were significantly associated with good prognosis, while TGFB and EGFR pathway activation were associated with poor clinical outcome." (PMID 21050467, 2010). "One of the best known breast cancer oncogenes is HER2 (also known as neu, ErbB-2, and NGL) which belongs to the epidermal growth factor receptor (EGFR) family and encodes an 185 kDa transmembrane receptor tyrosine-kinase." (PMID 21044318, 2010).
breast carcinoma (continued). "A positive correlation between nuclear EGFR and cyclin D1 expression was observed both in mammary gland samples and breast cancer samples of cancer-bearing TA2 mice." (PMID 20092659, 2010). "Met also is overexpressed in breast cancer cells and human breast tumors and its expression correlates with EGFR expression in basal type breast cancers." (PMID 20624308, 2010). "Overexpression of the EGFR has been shown to correlate with metastasis and poor prognosis of breast cancer." (PMID 20074374, 2010). "Involvement of EGF signalling in the pathogenesis of bone metastasis was implicated by the unexpected relief of bone pain in phase II clinical trials of EGFR inhibitor gefitinib in breast cancer patients." (PMID 20010942, 2010). "EGFR tyrosine kinase inhibitors (TKIs) are in clinical use in lung and pancreatic cancers, but have yet to demonstrate efficacy in breast cancer." (PMID 20624308, 2010). "To summarize, we have found that expression of versican G3 promoted breast cancer cell growth and metastasis through up-regulating active EGFR expression and activation of the EGFR-mediated pathway." (PMID 21079779, 2010). "Recent findings suggest the important role of EGFR (or similar receptors) for estrogen signaling from the membrane in breast cancer." (PMID 21124760, 2010). "• Activity of the EGFR signalling pathway was highest in the basal and normal subtypes of ER- breast cancer in line with the higher levels of EGFR in these tumours (P < 10-8)." (PMID 21050467, 2010). "In spontaneous breast cancer-bearing mice, stronger EGFR staining was observed in mammary gland samples when compared to tumor samples, and nuclear translocation was observed in both tissue types." (PMID 20092659, 2010). "In vitro, G3 enhanced breast cancer cell proliferation and migration by up-regulating EGFR signaling, and enhanced cell motility through chemotactic mechanisms to bone stromal cells, which was prevented by inhibitor AG 1478." (PMID 21079779, 2010). "Over-expression of EGF and its receptor (EGFR) has been found in many human tumors and cell lines, including breast cancer." (PMID 21079779, 2010). "Secondly, our findings indicate that captured CTCs are amenable to biomarker analyses such as HER2 status, qRT-PCR for breast cancer subtype markers, KRAS mutation detection, and EGFR staining by IF." (PMID 20838621, 2010). "The presence of two EGF-like domains in versican G3 and the importance of versican as a prognostic factor in breast cancer add to the interest in further delineating the role of EGFR and downstream signaling in invasive breast cancer." (PMID 21079779, 2010). "Basal-like TN breast cancers express basal markers such as cytokeratin 5/6 and epidermal growth factor receptor." (PMID 21050424, 2010). "This study aims to verify the significance of CXCR4, CCR7 and their CXCL12 and CCL21 ligands, together with EGFR in the evaluation of metastasis and the prognosis of breast cancer." (PMID 20181250, 2010). "EGFR/HER family receptors play key roles in breast cancer metastasis and their expression are correlated with worse prognostic patient survival rates." (PMID 20074374, 2010). "Lastly, inhibiting EGFR and Met kinase activities resulted in a synergistic decrease in cell proliferation, supporting the idea that EGFR and Met functionally, as well as physically interact in breast cancer cells to regulate response to EGFR inhibitors." (PMID 20624308, 2010). "EGF withdrawal was previously documented to transform human breast epithelial cell line HMT-3522, where EGFR suppression was posited to promote estrogen-responsive breast cancer." (PMID 20809984, 2010). "In breast cancer, Src interacts with EGFR, enhancing the activation of mitogenic signaling and promoting cancer progression." (PMID 20955590, 2010). "Lapatinib (formerly known as GW572016) is currently the most advanced oral selective dual-EGFR/HER2 reversible inhibitor in terms of clinical development in breast cancer." (PMID 21050422, 2010).
breast carcinoma (continued). "We demonstrate that captured CTCs are amenable to biomarker analyses such as HER2 status, qRT-PCR for breast cancer subtype markers, KRAS mutation detection, and EGFR staining by immunofluorescence (IF)." (PMID 20838621, 2010). "E-cadherin staining in the tissue samples is observed both at the membrane and in the cytoplasm, as autocrine EGFR signaling generally present in breast cancer drives E-cadherin internalization." (PMID 20609236, 2010). "In sFRP1 knockdown breast cancer cell lines, EGFR is transactivated, indicating a synergistic effect of Wnt and EGFR signaling in breast cancer development." (PMID 20828404, 2010). "In this study we demonstrated that G3 enhances mouse mammary tumor cell growth, migration, proliferation and metastasis through up-regulating EGFR signaling." (PMID 21079779, 2010). "The activity of G3 on mouse mammary tumor cell growth, migration and its effect on spontaneous metastasis to bone in an orthotopic model was modulated by up-regulating the EGFR-mediated signaling pathway." (PMID 21079779, 2010). "Expression of PIPKIγ correlated positively with epidermal growth factor receptor (EGFR) expression, which regulates breast cancer progression and metastasis." (PMID 20074374, 2010). "Both EgfR and ErbB2 are overexpressed in a substantial fraction of breast cancers and are recognized targets for breast cancer therapy." (PMID 19317917, 2009). "In breast carcinomas with EGFR over-expression, NF-κB was reportedly activated, which was also linked to unfavorable prognosis by promoting tumor metastasis and inhibiting apoptosis." (PMID 19442295, 2009). "HER1 (or EGFR) has been described as both a prognostic marker and a predictor of hormone-therapy resistance in breast cancer." (PMID 19638208, 2009). "We have studied the combination of IAP targeting and growth factor receptor inhibition in breast cancer cell lines, where overexpression of the EGFR or Her2 is common." (PMID 19563669, 2009). "The EGFR gene isfrequently altered by gene amplification or overexpression at the mRNA andprotein levels in sporadic breast cancer cases." (PMID 19390622, 2009). "Crosslinking α6β4 integrin in breast carcinoma cells induces EGFR clustering and preferentially promotes Rho activation in response to EGF, with only minimal effects on Akt and Erk 1,2 phosphorylation." (PMID 19470173, 2009). "Itis hoped that reviews like this can help to elucidate the mechanismsinvolved in anti-EGFR therapy as well as define relationships between the overexpressionof EGFR and other biomarkers of breast cancer." (PMID 19390622, 2009). "Increasingly, there is recognition andacceptance of the unique role anti-EGFR therapy plays in the armamentarium oftreatment options available to breast cancer patients." (PMID 19390622, 2009). "HER2 belongs to the human epidermal growth factor receptor (EGFR) family and is amplified in about 10–20% of breast carcinomas causing an increased expression of its protein." (PMID 19123950, 2009). "Anti-EGFR therapy has found application for casesfrom all three major breast cancer subclasses, respectively, thehormone-sensitive/insensitive group, the ER+/− and HER-2/neu+/− groups, and thebasal-like/triple negative (−) group." (PMID 19390622, 2009). "EGFR and ER are also frequently co-expressed in normal-appearing cells obtained from breast cancer patients." (PMID 22276018, 2009). "Here we report the effects of adhesion-independent α6β4 integrin crosslinking on the distribution and function of EGFR in MDA-MB-231 breast carcinoma cells, known to express high levels of α6β4 integrin and EGFR typical of basal-like breast carcinomas." (PMID 19470173, 2009). "Dysfunctional EGFR-signaling networks are reportedly presentin a cohort of breast carcinomas with poor prognosis." (PMID 19390622, 2009).
breast carcinoma (continued). "Based on studies in female patients with breast cancer, EGFR was reportedly over-expressed in aggressive and metastatic breast carcinomas." (PMID 19442295, 2009). "MDA-MB-231 breast carcinoma cells express α6β4 and EGFR and have been shown to produce pulmonary metastases in nude mice." (PMID 19470173, 2009). "One study reported high expression of EGFR to be inversely correlated with nodal metastases and shorter, distant disease-free survival in a group of breast cancer patients who had received 2 years of adjuvant tamoxifen treatment." (PMID 19935798, 2009). "We observed that crosslinking α6β4 integrin in breast carcinoma cells in suspension induced cell surface clustering of EGFR." (PMID 19470173, 2009). "Recently, advances in anti-EGFR therapyhave given hope to the development of new breast cancer therapies with improvedspecificity, activity, and safety." (PMID 19390622, 2009). "Crosslinking α6β4 integrin in breast carcinoma cells induces EGFR clustering and preferentially promotes Rho activation in response to EGF." (PMID 19470173, 2009). "We evaluated the effects of α6β4 crosslinking on the distribution and function of EGFR in breast carcinoma cell line MDA-MB-231." (PMID 19470173, 2009). "These strategies have been successful in the area of breast cancer and EGFR has been effective in the treatment of metastatic colorectal cancer." (PMID 19118499, 2009). "Cheang reported that the expanded surrogate of PgR, HER2, EGFR, and cytokeratin 5/6 indicate a more specific definition of basal-like breast cancer, mostly TNBC, which better predicts breast cancer survival." (PMID 19534825, 2009). "Similar to the role of androgens in PCa, oestrogens regulate the expression and activity of EGFR in breast cancer." (PMID 19888222, 2009). "It was also reported that transcription factor nuclear factor κB (NF-κB) was activated in breast cancer cells with over-expressed EGFR." (PMID 19442295, 2009). "EGFR is also overexpressed in the basal subtype of breast cancer, and crosstalk between α6β4 integrin and EGFR appears to be important in tumor progression." (PMID 19470173, 2009). "To that end, we mapped genomic, transcriptional and proteomic profiles for 30 breast cancer cell lines onto a curated Pathway Logic symbolic systems model of EgfR-MAPK signaling." (PMID 19317917, 2009). "This review will focus on recent advances in the application of antiepidermal growth factor receptor (anti-EGFR) for the treatment of breast cancer." (PMID 19390622, 2009). "Glucose transport and phosphorylation were increased significantly in MDA–MB-468 breast cancer cells expressing a high number of EGFR." (PMID 19888222, 2009). "We have previously shown that the WNT pathway influences proliferation of breast cancer cell lines via activation of canonical signaling and epidermal growth factor receptor transactivation, and that interference with WNT signaling reduces proliferation." (PMID 19473496, 2009). "The data on EGFR expression in male breast cancer are very limited with only a few earlier studies conducted more than a decade ago." (PMID 19442295, 2009). "Epidermal growth factor receptor (EGFR) was reported to be over-expressed in aggressive female breast cancer and is currently being evaluated in clinical trials as a potential therapeutic target." (PMID 19442295, 2009). "Deregulation in signaling along the EgfR-MAPK pathway is common in breast cancer, though the manner in which deregulation occurs varies between both individuals and cancer subtypes." (PMID 19317917, 2009). "This subset included known breast cancer genes, like EGFR (7p11), FGFR1 (8p12), ERBB2 (17q12), PPM1D (17q23) and ZNF217 (20q13)." (PMID 19582160, 2009). "Nearly 45% of human breast tumours express EGFR and previous studies reported an inverse correlation between EGFR and ER expression in breast cancer." (PMID 22276018, 2009).
breast carcinoma (continued). "EGFR has been shown to co-immunoprecipitate with α6β4, and EGFR is co-expressed with α6β4 in breast cancers that tend to metastasize to the lungs." (PMID 19470173, 2009). "The reported expression rate of EGFR in male breast carcinomas varied significantly from 8.5% to 76%, probably due to variations in antibody preparation, staining protocol, and interpretation criteria." (PMID 19442295, 2009). "We were interested in identifying subnetworks within the EgfR-MAPK pathway that are similarly deregulated across subsets of breast cancers." (PMID 19317917, 2009). "A recent study reported that the gene expression profile associated with insulin-like growth factor treatment of MCF7 cells contained significant overlap with gene signatures derived from breast cancer cell lines that over-expressed EGFR and ERBB2." (PMID 19552798, 2009). "We found that EGFR expression was maintained at similar levels in the plasma and in the mammary tumors after goserelin administration, both during acute and chronic treatment." (PMID 19491505, 2009). "Epidermal growth factor receptor (EGFR) is over-expressed in a wide variety of epithelial malignancies including non-small cell lung, head and neck, colon, and breast cancers." (PMID 18302761, 2008). "Significantly we found that silencing of BCAR1, a proposed downstream mediator of TNK2, inhibits breast cancer cell invasion via a mechanism distinct from the EGFR." (PMID 18435854, 2008). "The epidermal growth factor receptor (EGFR)-related tyrosine kinase Her2 is an important therapeutic target in breast cancer." (PMID 18834540, 2008). "We have shown that HER3 phosphorylation was suppressed by Iressa upon acute treatment in three breast cancer cell lines as well as A431 cells through suppression of EGFR/HER3 dimerization." (PMID 18682844, 2008). "Because of the effect of TNK2 siRNA on the cell surface EGFR population, we wanted to determine the effect of EGFR activation on breast cancer cell behaviour." (PMID 18435854, 2008). "Led by the success of trastuzumab's HER2 blocking capabilities in breast cancer, EGFR inhibition with an emphasis on HER2 inhibition continues to be an area of focus in the treatment of breast cancer patients." (PMID 18828924, 2008). "EGFR is frequently over-expressed in breast cancers, and EGFR signaling is correlated with poor patient outcome." (PMID 18822183, 2008). "Increased expression of EGFR has been demonstrated elsewhere to suggest a poor prognosis in breast cancer." (PMID 18474099, 2008). "We also analyzed EGFR gene copy numbers of TNBCs by the PCR method, and found frequent increases in TNBCs compared with luminal subtype breast cancers." (PMID 18950515, 2008). "Mutated EGFR has been found in a subset of NSCLCs, and ERBB2 is amplified and over-expressed in up to 30% of human breast cancers, which is associated with a poorer clinical outcome." (PMID 19019207, 2008). "EGFR-mediated signaling has been correlated with disease stage and the development of tumor metastasis in breast cancer." (PMID 18320059, 2008). "Up to 25% of patients diagnosed with breast cancer have tumours that overexpress the EGFR-2 (HER2 or Erb B-2)." (PMID 18665178, 2008). "This is of particular importance in BLBC given the role of EGFR signaling in this particular type of breast cancer." (PMID 19036157, 2008). "While the emphasis of this study has been on BLBC, EGFR is equally important in promoting growth signals in other types of breast cancer." (PMID 19036157, 2008). "In the present article we demonstrate the efficacy of targeting TNK2, a nonreceptor tyrosine kinase, by siRNA, and its effect on inhibiting EGFR cell surface expression and the migration and invasion of breast cancer cells." (PMID 18435854, 2008).